TUBA1C (tubulin alpha 1c)
Diseases named in the same sentence as TUBA1C in open-access papers (continued):
Sharing a sentence is not in itself a finding about the gene and the disease.
breast carcinoma (continued). "In this study, sequencing data, clinical information, and follow-up data for patients were extracted from The Cancer Genome Atlas (TCGA) to evaluate the differential expression of TUBA1C between breast cancer patients and healthy individuals, after which a pairwise comparison was performed." (PMID 38032902, 2023). "Observation of the gene expression profile suggests that TUBA1C might play an important role in breast cancer." (PMID 38032902, 2023). "In addition, the abnormally high TUBA1C expression in breast cancer tissues was closely related to survival status, survival time, and tumor size." (PMID 38032902, 2023). "The TCGA data included 1085 breast cancer samples with information on TUBA1C expression." (PMID 38032902, 2023). "However, the study design had some limitations, and additional prospective studies and experiments are still needed to reveal the biological function of TUBA1C in breast cancer." (PMID 38032902, 2023). "According to previous research, high TUBA1C expression can promote cell proliferation, which may lead to the poor prognosis of breast cancer patients." (PMID 38032902, 2023). "The results demonstrated that TUBA1C is a potential prognostic biomarker of breast cancer." (PMID 38032902, 2023). "However, few studies on TUBA1C in breast cancer have been published." (PMID 38032902, 2023). "The correlations between TUBA1C and the TOLL-like receptor signaling pathway and the NOD-like receptor signaling pathway in breast cancer were first reported in this study, but the specific regulatory mechanisms remain to be further elucidated." (PMID 38032902, 2023). "Although other studies have included TUBA1C in the screening of differentially expressed genes in breast cancer, the focus of these studies was not TUBA1C, and thus, the correlation between TUBA1C and the prognosis of breast cancer patients has not been thoroughly studied." (PMID 38032902, 2023). "However, the correlations between abnormally elevated TUBA1C expression and breast cancer prognosis as well as other clinical factors of breast cancer have not been clearly elucidated." (PMID 38032902, 2023).
hepatocellular carcinoma (11 papers, 2017 to 2024). A malignant tumor that arises from hepatocytes. "TUBA1C overexpression predicts a poor prognosis in hepatocellular carcinomas (HCCs) and promotes cell proliferation and migration." (PMID 37528357, 2023). "High TUBA1C expression has also been reported in hepatocellular carcinoma (HCC) and pancreatic ductal adenocarcinoma (PDAC), where it was an indicator of the poor prognosis and facilitated tumor cell proliferation and migration." (PMID 36941595, 2023). "Moreover, TUBA1C is a subtype of α-tubulin, and its overexpression is associated with the poor prognosis of hepatocellular carcinoma (HCC) and pancreatic ductal adenocarcinoma." (PMID 33653340, 2021). "In conclusion, prognostic biomarker and oncogene TUBA1C promotes migration and proliferation of hepatocellular carcinoma cells, probability via cell cycle signaling pathway." (PMID 29221200, 2017). "In summary, TUBA1C expression alters prognosis of hepatocellular carcinoma may via cell cycle signaling pathway." (PMID 29221200, 2017). "TUBA1C was found to be upregulated in hepatocellular carcinoma (HCC) and pancreatic ductal adenocarcinoma (PDAC), where it predicted poor prognosis and facilitated cell proliferation and migration." (PMID 35513790, 2022). "Additionally, TUBA1C is upregulated in hepatocellular carcinoma (HCC) and pancreatic ductal adenocarcinoma (PDAC), where it predicts poor prognosis and enhances cell proliferation and migration." (PMID 39355251, 2024). "Moreover, TUBA1C, a subtype of α-tubulin, which is composed of microtubule structure, was reported to be overexpressed and predicts poor prognosis and promotes cell proliferation and migration in hepatocellular carcinoma (HCC)." (PMID 32117719, 2020).
pancreatic ductal adenocarcinoma (9 papers, 2020 to 2024). An infiltrating adenocarcinoma that arises from the epithelial cells of the pancreas. "TUBA1C has been identified as a key gene that promotes tumorigenesis and is a potential new cancer target, and according to the literature, silencing TUBA1C inhibits pancreatic ductal adenocarcinoma cell proliferation, migration, and invasion." (PMID 37528357, 2023). "The TUBA1C gene regulates the cell cycle and promotes pancreatic ductal adenocarcinoma cell invasion and migration." (PMID 37528357, 2023). "As a subtype of α-tubulin, TUBA1C has remarkably elevated expression in tumour tissues compared with normal tissues, and its upregulation indicates a dismal prognosis of pancreatic ductal adenocarcinoma." (PMID 36466547, 2022). "Previous studies have shown that elevated expression of TUBA1C leads to an unfavourable prognosis in pancreatic ductal adenocarcinoma." (PMID 36466547, 2022). "Moreover, TUBA1C, a subtype of α-tubulin, which is composed of microtubule structure, was reported to be overexpressed and promotes oncogenesis in pancreatic ductal adenocarcinoma via Regulating the cell cycle." (PMID 33618668, 2021). "Recently, several studies have proposed that TUBA1C is related to poor prognosis in HCC, pancreatic ductal adenocarcinoma, and lung adenocarcinoma." (PMID 34721547, 2021). "Notably, overexpression of TUBA1C, which is one of the α-tubulin subtypes is involved in the poor prognosis of HCC, pancreatic ductal adenocarcinoma, and lung cancer." (PMID 34721547, 2021).
lung adenocarcinoma (8 papers, 2021 to 2024). A carcinoma that arises from the lung and is characterized by the presence of malignant glandular epithelial cells. "The overexpression of TUBA1C has been correlated with poor prognosis in patients with lung adenocarcinoma (LUAD) and is associated with 13 types of tumor-infiltrating immune cells (TIICs) in the tumor microenvironment." (PMID 38891892, 2024). "The ATM mutated patients with TUBA1C low expression showed better survival than patients with over-expression of TUBA1C in lung adenocarcinoma (LUAD) (P = 0.03, log-rank test)." (PMID 36180906, 2022). "TUBA1C is an isoform of α-tubulin that has been shown to play a critical role in the cell cycle and immune microenvironment of lung adenocarcinoma (LUAD)." (PMID 39355251, 2024). "The function of TUBA1C in the tumorigenesis of solid tumors such as liver, breast, ovarian, and lung adenocarcinomas have been described previously; however, its role in GC remains to be explored." (PMID 36941595, 2023). "Multivariable analysis demonstrated that only the TUBA1C expression was an independent prognostic factor in lung adenocarcinoma." (PMID 33653340, 2021). "Our main objective was to investigate TUBA1C expression, its prognostic value, its potential biological functions, and its impact on the immune system of patients with lung adenocarcinoma (LUAD)." (PMID 33653340, 2021). "In future clinical practice, the expression of TUBA1C in lung adenocarcinoma tissue may be used to predict the prognosis and the efficacy of immunotherapy of patients." (PMID 33653340, 2021). "Similarly, a previous study has illustrated that TUBA1C relates to the tumor-infiltrating cells of lung adenocarcinoma." (PMID 34721547, 2021). "Notably, elevated TUBA1C expression displayed a significant positive correlation with CNV in ccRCC and lung adenocarcinoma (LUAD), among other cancer types." (PMID 39301023, 2024).
lung carcinoma (7 papers, 2021 to 2024). "For example, knock-down TUBA1C by shRNA in lung cancer cells with ATM mutation showed a worse survival than cells with wild-type ATM (P = 0.01, one-sided Wilcoxon rank-sum test)." (PMID 36180906, 2022). "Interestingly, among the top 6 co-expressed genes of PSMD2, the EIF4G1 and TUBA1C were reported to be related to immune infiltration in lung cancer, and EIF4G1 is significantly associated with the PD-L1 expression." (PMID 36505799, 2022). "Studies targeting lung cancer, liver cancer, and pancreatic cancer have all confirmed that TUBA1C promotes tumorigenesis and progression and is a potential prognostic biomarker for liver cancer and pancreatic cancer." (PMID 38032902, 2023). "In addition, TUBA1C can also negatively regulate miR-143-3p to promote the proliferation of lung cancer cells and reduce cancer cell apoptosis." (PMID 38032902, 2023). "Although the role of TUBB in mediating immune cell infiltration has not been investigated extensively, several members of the tubulin family have been shown to play a role in immune cell infiltration including TUBA1C, which mediates immune infiltration in lung cancer." (PMID 36140469, 2022). "Moreover, TUBA1C are found to be involved in the growth, invasion, and metastasis of lung cancer." (PMID 39628476, 2024). "TUBA1C, GAPDH, KRT25, GCC2, and POTEKP were the five proteins identified as potential lung cancer-specific exosome biomarkers." (PMID 34771645, 2021). "This study proved for the first time that the exosomes secreted by lung cancer cell line H1299 could significantly change the expression of apoptosis related proteins MAP2K1, TUBA1C, RELA, and CASP6, thus promoting apoptosis of human astrocyte line SVG P12 cells." (PMID 36859173, 2023).
pancreatic cancer (6 papers, 2020 to 2023). "For example, abnormally elevated TUBA1C expression in pancreatic cancer cells is associated with the prognosis of pancreatic cancer patients." (PMID 38032902, 2023). "A comparison of SEL1L/TUBA1C/SDC1 mRNA expression levels in various pancreatic cancer cell lines using the Cancer Cell Line Encyclopedia (CCLE) database showed that most pancreatic cancer cells expressed less SEL1L than SDC1 or TUBA1C." (PMID 38048216, 2023). "High expression of TUBA1C in TCGA-pancreatic cancer cohort included 143 upregulated genes and 42 downregulated genes." (PMID 38048216, 2023). "Pancreatic cancer samples had a higher expression of TUBA1C and SDC1 compared with the standard samples, while SEL1L expression was lower in vitro and in vivo." (PMID 38048216, 2023). "Western blotting (WB) assay was employed to evaluate the expression of TUBA1C in pancreatic cancer cell lines." (PMID 32117719, 2020). "Kaplan–Meier survival analysis of data from TCGA showed that pancreatic cancer patients with higher expression of TUBA1C had shorter OS and DFS." (PMID 32117719, 2020). "The results confirmed that knockdown of TUBA1C significantly inhibited the pancreatic cancer cell proliferation (AsPC-1 and BxPC-3) (P < 0.05) and enhanced the cell apoptosis in AsPC-1 and BxPC-3 cell lines (P < 0.05)." (PMID 32117719, 2020). "Positive staining was observed in the cytoplasm of the pancreatic tumor cells, and the level of TUBA1C staining was significantly upregulated in PDAC tissue compared with adjacent non-tumor tissues." (PMID 32117719, 2020). "Patients with pancreatic cancer have shorter OS when TUBA1C is overexpressed." (PMID 38048216, 2023). "Studies have reported that knockout of TUBA1C in vitro can significantly inhibit the proliferation of pancreatic cancer cells and promote apoptosis, and TUBA1C expression may alter the prognosis of HCC through cell cycle signalling." (PMID 36466547, 2022). "Differential expression of TUBA1C in pancreatic cancer and adjacent tissues." (PMID 32117719, 2020). "Furthermore, the expression of TUBA1C was determined using tissue microarray-based immunohistochemistry with 99 human pancreatic tumor samples and 71 adjacent tissues." (PMID 32117719, 2020). "The SEL1L/TUBA1C/SDC1 mRNA expression levels were compared in normal and pancreatic cancer tissues using TCGA." (PMID 38048216, 2023). "Immune infiltration data from the high- and low-expression SEL1L, TUBA1C, and SDC1 pancreatic cancer groups were gathered using CIBERSORT algorithms." (PMID 38048216, 2023). "TCGA-pancreatic cancer data were classified according to NRG expression levels, SEL1L, TUBA1C, and SDC1, and each group was analyzed using GO and KEGG." (PMID 38048216, 2023). "We identified 12 GRGs differently expressed in pancreatic cancer and selected three genes (SEL1L, TUBA1C, and SDC1) to build a prognostic model." (PMID 38048216, 2023). "Additionally, we compared the levels of SEL1L/TUBA1C/SDC1 expression in normal and pancreatic cancer tissues using the Human Protein Atlas (HPA) database." (PMID 38048216, 2023). "We identified three GRGs closely related to pancreatic cancer: SEL1L, TUBA1C, and SDC1." (PMID 38048216, 2023). "Human pancreatic cancer tissue and adjacent non-tumor tissues samples were detected by immunochemistry (IHC) staining, and the correlation between TUBA1C expression and the clinicopathological features were investigated." (PMID 32117719, 2020).
bladder cancer (4 papers, 2021 to 2024). "In three independent public cohorts, TUBA1C was significantly upregulated in bladder tumor tissues, and high TUBA1C expression in bladder cancer was associated with a poorer outcome than low expression." (PMID 37528357, 2023). "TUBA1C was an independent prognostic risk factor for bladder cancer, and numerous immune checkpoint genes and infiltrating immune cells were associated with TUBA1C." (PMID 37528357, 2023). "TIDE analysis revealed that TUBA1C showed great potential for predicting the immunotherapy response in bladder cancer patients." (PMID 37528357, 2023). "Differential expression of TUBA1C was assessed using data from GSE13507 (which includes information on 10 normal bladder tissues and 165 bladder cancer tissues), and TUBA1C expression was found to be elevated in BLCA (P < 0.001)." (PMID 37528357, 2023). "Additionally, we examined the functional mechanism of TUBA1C in bladder cancer to determine its prognostic significance." (PMID 37528357, 2023). "The overexpression of TUBA1C in bladder cancer predicts a poor prognosis and may also be a potential immunotherapeutic target." (PMID 37528357, 2023).
acute myeloid leukaemia (3 papers, 2020 to 2022). "Intriguingly, lower expression of TUBA1C was noted in acute myeloid leukaemia (LAML)." (PMID 35513790, 2022).
gastric cancer (3 papers, 2022 to 2024). A primary or metastatic malignant neoplasm involving the stomach. "TCGA databases also show that TUBA1C mRNA is upregulated in a variety of malignancies including colon, esophagus, lung, hepatocellular and gastric cancers." (PMID 36941595, 2023). "TUBA1C is a new potential target of LncRNA EGFR-AS1 promotes gastric cancer progression and could be a novel biomarker and therapeutic target for GC." (PMID 36941595, 2023). "TUBA1C was proved to be a direct target of EGFR-AS1, and TUBA1C promotes gastric cancer proliferation, migration and invasion by accelerating the progression of the cell cycle from the G1 phase to the S phase and activating the expression of oncogenes: Ki-67, E2F1 and PCNA." (PMID 36941595, 2023). "Tubulin alpha-1 C (TUBA1C) is a subtype of α-tubulin, high TUBA1C expression has been shown to be closely related to a poor prognosis in various cancers, this study, for the first time, revealed the mechanism of TUBA1C promotes malignant progression of gastric cancer in vitro and in vivo." (PMID 36941595, 2023). "Further analysis in vitro showed that TUBA1C influenced the expression of the oncogenes: Ki-67, E2F1 and PCNA, and promote malignant progression of gastric cancer cells by affecting the cell cycle." (PMID 36941595, 2023). "However, there is no literature reporting the role of TUBA1C molecule in the development and metastasis of gastric cancer." (PMID 36941595, 2023). "We found TUBA1C is a new potential target of LncRNA EGFR-AS1 promotes gastric cancer progression, the cancer-promoting function of lncRNA EGFR-AS1 in GC is partially mediated by heightening EGFR mRNA stability to active PI3K/AKT pathway and EGFR-AS1-TUBA1C interactions." (PMID 36941595, 2023).
liver cancer (3 papers, 2019 to 2023). An epithelial or non-epithelial malignant neoplasm that arises from the liver. "Related research reports confirm that TUBA1C can promote liver cancer cell proliferation and invasion and can be used as a prognostic indicator in liver cancer." (PMID 38032902, 2023).
E. coli infection (2 papers, 2019 to 2021). "Enrichment analysis using the KEGG database revealed the significant participation of detected proteins in pathogenic E. coli infection (ACTG1, TUBA1C, TUBA4A, TUBB, TUBB8, and YWHAZ), which may indicate microbiota changes associated with being in space." (PMID 31547269, 2019).
glioblastoma (2 papers, 2020 to 2022). The most malignant astrocytic tumor (WHO grade IV). "TUBA1C expression was highest in primary glioblastoma (pGBM) and recurrent pGBM (rGBM) and lowest in astrocytoma (A)." (PMID 35513790, 2022). "The CDK4/CDK6 and TUBA1C mRNA levels were higher in glioblastomas than those in normal brain tissues." (PMID 32860670, 2020).
kidney cancer (2 papers, 2022 to 2024). Primary or metastatic malignant neoplasm involving the kidney. "In our study, utilizing the DepMap database, we investigated the effects of TUBA1C knockout on the phenotypes of kidney cancer cell lines and examined the relationship between TUBA1C mutations and the efficacy of anti-PD-L1 therapy." (PMID 39301023, 2024). "These cancer types demonstrated a similar relationship between TUBA1C mutation and sensitivity to anti-PD-L1 therapy as that seen with the kidney cancer lines." (PMID 39301023, 2024). "Additionally, TUBA1C dependency and its effects were evident in kidney cancer cell lines, where mutations conferred resistance to anti-PD-L1 therapy." (PMID 39301023, 2024). "Intriguingly, kidney cancer cell lines with wild-type TUBA1C displayed a higher CD274 dependency score than their mutant counterparts." (PMID 39301023, 2024). "Functional studies involving 26 kidney cancer cell lines demonstrated that TUBA1C is essential for their proliferation and survival." (PMID 39301023, 2024). "Finally, the RNA expression levels and oncogenic functions of TUBA1C were further validated in kidney cancer cell lines." (PMID 39301023, 2024). "Additionally, we conducted a bioinformatics analysis using various kidney cancer cell lines to demonstrate the effects of TUBA1C gene function on the cellular phenotypes." (PMID 39301023, 2024).
ovarian carcinoma (2 papers, 2022). A malignant neoplasm originating from the surface ovarian epithelium. "As a note, Tuba1c has been recently proposed as ovarian cancer marker." (PMID 35406774, 2022).
paraganglioma (2 papers, 2022 to 2023). A benign or malignant neoplasm arising from paraganglia located along the sympathetic or parasympathetic nerves. "The mRNA expression of TUBA1C was downregulated in only pheochromocytoma and paraganglioma (PCPG)." (PMID 36466547, 2022).
Parkinson disease (2 papers, 2023 to 2024). A progressive degenerative disorder of the central nervous system characterized by loss of dopamine producing neurons in the substantia nigra and the presence of Lewy bodies in the substantia nigra and locus coeruleus. "A decreased expression of the TUBA1C gene in Parkinson's disease has already been demonstrated by quantitative analysis of gene expression." (PMID 36970516, 2023). "Here, Tuba1c was also identified as a significant gene in the gene enrichment KEGG pathway analysis including, apoptosis, pathways of neurodegeneration, ALS, and Parkinson disease." (PMID 38438964, 2024).
prion disease (2 papers, 2022 to 2023). A transmissible disease that is caused by a protein that is able to induce abnormal folding of normal cellular proteins, leading to characteristic spongiform brain changes, which are associated with neuronal loss without an inflammatory response. "Interestingly, observed enrichment in the following biological pathways: Alzheimer’s disease, PD, pathways of neurodegeneration, gap junction, prion disease, and Huntington’s disease, all had Tuba1c as a significant up-regulated gene in the enriched pathways." (PMID 36172466, 2022).